PVALB (parvalbumin)
Diseases named in the same sentence as PVALB in open-access papers (continued):
Sharing a sentence is not in itself a finding about the gene and the disease.
schizophrenia (continued). "Expression of DISC1ΔC under the control of the CaMKII promoter in a transgenic mouse line resulted in several phenotypes related to schizophrenia including enlarged lateral ventricles, reduction in parvalbumin immunoreactivity, reduced cortical dopamine levels and behavioral abnormalities." (PMID 22479520, 2012). "Parvalbumin was also decreased in autism, schizophrenia, and bipolar disorder." (PMID 22936973, 2012). "For instance, expression of parvalbumin, a marker of mature fast-spiking inhibitory neurons is decreased in individuals with schizophrenia and bipolar disorder and in several mouse models of schizophrenia and autism." (PMID 22936973, 2012). "We also review current models for the mechanisms of GABA-mediated synchronization of neural activity, focusing on parvalbumin-positive GABA neurons, which are altered in schizophrenia and whose function has been strongly linked to the production of neural synchrony." (PMID 21904685, 2011). "Furthermore, parvalbumin-positive neurons, which are mostly GABAergic and closely involved in the pathologies of schizophrenia and autism, were analyzed in the amygdala, hippocampus, and medial prefrontal cortex." (PMID 21437241, 2011). "Parvalbumin (PVALB) is a calcium binding protein primarily expressed in high-frequency firing inhibitory neurons, which are also vulnerable in AD and other neurological diseases such as many psychiatric disorders, such as schizophrenia, autism spectrum disorders, and substance abuse." (PMID 41282152, 2025). "D3R signaling is emerging as a possible regulatory mechanism of parvalbumin neuron-dependent gamma oscillations (γ-oscillations are believed to be a major organizer of brain functional networking and have been demonstrated to be abnormal in schizophrenia patients)." (PMID 36983018, 2023). "The NMDAR hypofunction hypothesis predicts a reduced function of parvalbumin-positive fast-spiking GABA interneurons considered a major determinant of schizophrenia molecular pathophysiology with a possible role in poor response to antipsychotics acting at D2R." (PMID 36983018, 2023). "Thus, HCN channels in parvalbumin-expressing basket cells might be a potential target for drug development for schizophrenia." (PMID 34709375, 2022). "Based on the findings of postmortem brain studies, the cortical parvalbumin-positive GABAergic neurons are impaired in the prefrontal cortex of patients with schizophrenia, and GABAergic compounds are challenged to compensate for the dysfunction of the GABAergic neurons in schizophrenia patients." (PMID 34997139, 2022). "Indeed, rodent models of schizophrenia consider the ventral hippocampus to be particularly vulnerable to threat induced stress, which is probably due to the distinct maturational profile of fast-spiking parvalbumin interneurons (PIV)." (PMID 34636951, 2022). "Previous genetic models of NMDAR hypofunction restricted to parvalbumin-positive interneurons indicate the necessity of an early postnatal impairment to trigger schizophrenia-like abnormalities, whereas the cellular substrates of NMDAR-mediated psychosis at adolescent/adult stages are unknown." (PMID 34899420, 2021). "Indeed, a decrease in the expression of parvalbumin in patients with SZ in different brain regions including the hippocampus and prefrontal cortex has been a consistent finding in human post-mortem studies and in animal models of schizophrenia." (PMID 32639965, 2020). "However, a reduction in Purkinje neurons in the cerebellum has been reported in subjects with schizophrenia, suggesting that this possibility may be more likely due to the contribution from other types of parvalbumin-expressing neurons in the cerebellum." (PMID 32639965, 2020). "Thus, our findings propose that the EF-hand calcium-binding proteins parvalbumin and calmodulin could be involved in the pathophysiology of schizophrenia in the cerebellum by altering calcium-dependent signalling pathways involved in synaptic function." (PMID 32639965, 2020).
schizophrenia (continued). "Therefore, this study measured a specific molecular subtype of parvalbumin interneuron and suggests that decreases in parvalbumin interneuron density in schizophrenia could be larger within discrete molecular classes of parvalbumin expressing interneurons." (PMID 31529297, 2019). "Our finding of reduced parvalbumin cell density in the pre-frontal cortex taken with other evidence implicating parvalbumin interneuron dysfunction, suggests that targeting parvalbumin interneurons may have potential as drug targets in the treatment of schizophrenia." (PMID 31529297, 2019). "Moreover, whether parvalbumin interneurons in the BLA of schizophrenia patients are altered is still unclear." (PMID 27432008, 2016). "Alternatively, several studies suggest that a reduction in parvalbumin expression rather than a loss of parvalbumin cells per se may be more characteristic of schizophrenia." (PMID 22238649, 2012). "Alongside the reduced expression of PVALB and the GABA synthetic enzyme GAD1/GAD67 in PFC, hippocampus and thalamic reticular nucleus in schizophrenia, PNN structure is also compromised." (PMID 41317238, 2025). "In the prefrontal cortex of a schizophrenia mouse model (disruption in schizophrenia, DISC1), both PNNs and parvalbumin-positive neurons were decreased." (PMID 40072050, 2025). "Alterations of GABAergic interneurons, particularly parvalbumin (PV) and somatostatin (SST) subtypes, are frequently observed in schizophrenia." (PMID 39381500, 2024). "Despite BDNF playing a critical role in the development and functionality of cortical parvalbumin neurons, the relationship between BDNF signaling impairments in these neurons and schizophrenia remains largely uncharacterized." (PMID 39125882, 2024). "Schizophrenia patients show decreased arborization and synaptic deficits in layer II/III pyramidal neurons, as well as alterations in parvalbumin-positive interneurons." (PMID 30617212, 2019). "Specifically, parvalbumin+ cells are now also being explored as a novel approach to repairing DLPFC neural circuitry and improving the cognitive symptom domain in schizophrenia (Clinicaltrials.gov Identifier: NCT03164876)." (PMID 30425662, 2018). "Despite the unchanged number of calcium-binding protein parvalbumin (PVALB) neurons, the reduced expressions of PVALB mRNA have been presented in patients with schizophrenia." (PMID 28358303, 2017). "Previous reports have shown that oxidative stress reduces parvalbumin expression in the PFC, which correlates with schizophrenia-like behavioral deficits." (PMID 28819639, 2017). "Parvalbumin mRNA levels were significantly reduced in PFC from these samples, however, as has been observed in PFC from several other cohorts of postmortem schizophrenia samples." (PMID 25786133, 2015). "Parvalbumin-positive GABA neurons are involved in neural synchrony and in the altered network oscillation in schizophrenia." (PMID 22457755, 2012). "pH accounted for significant amounts of variance in parvalbumin (12%), somatostatin (36%), DLG4 (13%) and PPP1R9B (11%) in the schizophrenia group." (PMID 22545112, 2012). "Interestingly, reduced expression of parvalbumin, GAD67, and reelin are highly replicated findings in the brains of schizophrenia patients." (PMID 40257019, 2025). "Evidence for reduced hippocampal parvalbumin in schizophrenia is more sparse, and negative reports for both regions have led to the proposal of a ‘low GABA marker’ subgroup, comprising approximately 50% of the patient population." (PMID 38363536, 2024). "Abnormalities in parvalbumin neurons and impairments in evoked gamma oscillations are not specific to patients with schizophrenia." (PMID 39201380, 2024). "Several studies in schizophrenia patients found an altered expression of GABAA receptor subunits and GABA synthesis in the cerebral cortex, and electrophysiological dysfunction in parvalbumin and somatostatin GABAergic interneurons in the cortex and hippocampus." (PMID 34943962, 2021).
schizophrenia (continued). "Functional impairment of both types of PV (basket and chandelier) containing interneurons including the reduced expression of parvalbumin, GABA transporter (GAT)-1 mRNAs, and Gad1 (GAD67) all contribute to schizophrenia development (Lewis and González-Burgos, 2008)." (PMID 34055795, 2021). "We found reductions (21 – 44%) in mRNA encoding both presynaptic and postsynaptic proteins, vesicular GABA transporter (VGAT), GAD1, and parvalbumin (PV) mRNAs and four alpha subunits (α1, α2, α3, α5) of the GABAA receptor in people with schizophrenia compared to controls (p < 0.05)." (PMID 34174930, 2021). "Further validation in an independent cohort of non-suicidal chronic schizophrenia subjects (n = 13) and non-psychiatric controls (n = 14) showed that parvalbumin was increased, while calmodulin was decreased in schizophrenia." (PMID 32639965, 2020). "However, the expression of parvalbumin (PARV) and density of PARV-positive interneurons mostly appear unaltered in MDD, which is in contrast to schizophrenia." (PMID 32514634, 2020). "Reduced expression of GAD67 protein has been found in parvalbumin interneuron terminals, and a reduction in mean parvalbumin intensity has been measured in parvalbumin interneurons in schizophrenia without an alteration in PV neuron density." (PMID 32497062, 2020). "The results suggest that parvalbumin interneurons are reduced in density in the frontal cortex of patients with schizophrenia (Hedges’ g = − 0.27; p = 0.03) and there is a non-significant reduction in parvalbumin mRNA levels (g = − 0.44; p = 0.12)." (PMID 31529297, 2019). "The meta-analysis showed a non-significant reduction in parvalbumin mRNA in patients with schizophrenia when compared to healthy controls (Hedges’ g = − 0.44; z = − 1.56; p = 0.12; 95% CI − 0.99–0.12)." (PMID 31529297, 2019). "We found a significant reduction in parvalbumin cell density and a non-significant reduction in parvalbumin mRNA in patients with schizophrenia relative to healthy controls in pre-frontal cortical regions." (PMID 31529297, 2019). "The prevailing view, therefore, remains that in schizophrenia parvalbumin interneuron abnormalities exist not at the level of neuronal morphology or density, but at the molecular level of gene expression and protein synthesis." (PMID 31529297, 2019). "50% of the parvalbumin-positive neurons lack detectable amounts of GAD67 mRNA, whereas calretinin mRNA (which is expressed by a different subset of neurons—see Box 1) expression and the density of calretinin-positive neurons remain unchanged in schizophrenia." (PMID 28848455, 2017). "Reduction in parvalbumin expression in the BLA has been observed in some animal models of schizophrenia but not others." (PMID 27432008, 2016). "Our findings also support the involvement of Akt1 in the modulation of parvalbumin-positive interneurons and GABAergic signalling, thereby implicating Akt1 in the GABA hypothesis of schizophrenia." (PMID 27615800, 2016). "Similar to the findings in schizophrenia patients, these animals also show a reduction in mPFC levels of the GABA marker parvalbumin and impaired GABAergic inhibition of mPFC pyramidal neurons which is thought to underlie the selective EDS impairment seen in these subjects." (PMID 27467081, 2016). "Bioinformatics analysis of schizophrenia transcriptomics revealed functional co-clustering of FGF14 and genes enriched within the GABAergic pathway along with correlatively decreased expression of FGF14, PVALB, GAD67 and VGAT in the disease context." (PMID 27163207, 2016). "Bioinformatics analysis from human transcriptomics identified FGF14 as a component of GABAergic synaptic signaling and revealed a correlated decrease in FGF14, PVALB, GAD67 and VGAT gene expression in schizophrenia post-mortem tissues compared with matched controls." (PMID 27163207, 2016).
schizophrenia (continued). "Using an unbiased stereological method, we observed a decrease in the number of parvalbumin positive interneurons in the vSub and ventral DG of the hippocampus of rats with the MAM developmental disruption model of schizophrenia, consistent with previous findings." (PMID 27432008, 2016). "Human transcriptomics data confirmed functional clustering of FGF14 with GABAergic signaling and identified a highly correlated decrease of FGF14, PVALB, GAD67 and VGAT in schizophrenia post-mortem tissues, indicating possible genetic co-regulation of these genes." (PMID 27163207, 2016). "In order to put changes in TNFSF13 mRNA levels in the context of known schizophrenia neuropathology, we explored the relationship between levels of TNFSF13 mRNA and transcript levels of interneuron markers, somatostatin and parvalbumin, as well as spine markers, DLG4 and PPP1R9B." (PMID 22545112, 2012). "Interestingly, several postmortem studies found that neither the number of axons nor axonal morphology of PV+ interneurons is altered in schizophrenia but rather suggest that parvalbumin protein levels are downregulated." (PMID 40410588, 2025). "Abnormalities in parvalbumin positive GABAergic neurons, including reduced expression of GAD67, GAT1, and parvalbumin mRNA, as well as decreased dendritic branching and reduced somal size in pyramidal neurons, are thought to contribute to prefrontal cortical dysfunction in schizophrenia." (PMID 36816400, 2023). "Notably, many of the genes that are DE only in subjects that died at night are genes consistently implicated in schizophrenia in other DE studies (e.g., BDNF, PVALB, SST) which have not taken time of death into consideration (e.g.,18–24)." (PMID 31399567, 2019). "mGlu5 receptors are also present in parvalbumin-positive interneurons and parvalbumin-cell ablation of either NMDA or mGlu5 receptors alters the development and function of these neurons inducing core features of schizophrenia and other neurodevelopmental disorders." (PMID 30108503, 2018). "In animal models of schizophrenia, NAC has already been successfully used to prevent changes in sensory gating functions, as well as changes in parvalbumin-expressing interneurons, which are believed to be at the hub of many network changes in the brains of schizophrenic patients." (PMID 28634445, 2017). "As parvalbumin mRNA levels in schizophrenia tissue have been observed to correlate positively with pH in several studies and TNFSF13 expression correlated negatively with tissue pH in the current study, this means that as tissue pH is lowered, parvalbumin mRNA decreases but TNFSF13 mRNA increases." (PMID 22545112, 2012). "The dysfunction of parvalbumin-positive, fast-spiking interneurons (FSI) is considered a primary contributor to the pathophysiology of schizophrenia (SZ), but deficits in FSI physiology have not been explicitly characterized." (PMID 25290690, 2014). "A stereological study with immunohistochemical staining of interneurons in schizophrenia found lower numbers of somatostatin-expressing interneurons in CA4, CA2/3, and CA1 and of parvalbumin-immunoreactive interneurons in CA4 and CA1 but no changes in total neuron number." (PMID 36291109, 2022).
epilepsy (52 papers, 2010 to 2026). A brain disorder characterized by episodes of abnormally increased neuronal discharge resulting in transient episodes of sensory or motor neurological dysfunction, or psychic dysfunction. "Dysfunction of parvalbumin-positive (PV+) interneurons has been implicated in several neurological disorders, including epilepsy." (PMID 41408339, 2025). "In epilepsy, this tool can be used to understand the role groups of parvalbumin but normal and pathological mechanisms underlying the excitation-inhibition balance can be dissected." (PMID 35250498, 2022). "In this review, evidence from parvalbumin altered function in epilepsy and associated psychiatric comorbidities were explored with a translational perspective." (PMID 35250498, 2022). "Results showed the contents of parvalbumin-positive neurons were greatly decreased, and all the selenium-deficient mice died of fatal epilepsy by 18 days." (PMID 32908634, 2020). "Moreover, degeneration or functional silencing of specific GABAergic interneuron populations-such as parvalbumin-positive neurons in the subiculum-can induce epilepsy in rodent models and is likewise associated with TLE in humans." (PMID 41897358, 2026). "Functional data were incorporated into a parvalbumin‐positive (PV+) interneuron computer model to predict variant effects on neuron firing and were compared with longitudinal clinical data describing epilepsy types, neurocognitive outcomes, and medication response." (PMID 39838578, 2025). "Although it is still unclear how GABAergic and glutamatergic systems connect in this comorbidity puzzle, many discoveries compose and support the theory about the critical role of the parvalbumin inhibitory system and parvalbumin as the missing piece in psychosis behavior associated with epilepsy." (PMID 35250498, 2022). "Our novel findings of parvalbumin+ interneuron vulnerability vs calretinin+ interneuron resilience may occur in other types of mitochondrial encephalopathies, epilepsies and neurodevelopmental disorders associated with mitochondrial dysfunction." (PMID 35790454, 2022). "Some studies also reported that parvalbumin-positive interneurons altered function might contribute to psychiatric comorbidities associated with epilepsy, such as depression, anxiety, and psychosis." (PMID 35250498, 2022). "Thus, increased mTORC1-dependent translation in parvalbumin neurons is implicated in the pathophysiology of epilepsy." (PMID 35715811, 2022). "Thus, disproportionate sensitivity to low energy conditions could in part explain the finding of loss of parvalbumin-positive GABAergic interneurons in sclerotic hippocampus of epilepsy patients." (PMID 40659031, 2025). "Indeed, cilia dysfunction resulting from the selective loss of ciliary GTPase Arl13b affects cilia growth and also reduces the morphological complexity of parvalbumin-positive interneurons, a subset of inhibitory neurons implicated in multiple forms of epilepsy." (PMID 34445580, 2021). "While parvalbumin and calretinin are well-characterized CaBPs, N-Terminal EF-Hand Calcium-Binding Protein 1 (NECAB1) remains understudied in epilepsy, despite its association with neurodegenerative conditions." (PMID 40430045, 2025). "Parvalbumin (PV) neurons are the most widely studied neuronal subtype in epilepsy, as their inhibition can suppress neuronal spiking and prevent seizure onset." (PMID 40313715, 2025). "During the long pre-symptomatic phase, alterations in the function of Parvalbumin interneurons (PV-INs) are also observed, resulting in cortical hyperexcitability represented by subclinical epilepsy and aberrant gamma-oscillations." (PMID 38228889, 2024). "Activation of the TrkB receptor in animals with post-traumatic epilepsy hinders epileptogenesis through the modulation of parvalbumin interneurons." (PMID 38006577, 2024).